GDF15 (growth differentiation factor 15)
Diseases named in the same sentence as GDF15 in open-access papers (continued):
Sharing a sentence is not in itself a finding about the gene and the disease.
tumor (continued). "We undertook the present study to investigate the following in APC patients: (A) an appropriate cut-off value for serum GDF-15 levels; (B) the relationship between serum GDF-15 levels and clinical data; and (C) tumor characteristics associated with high serum levels of GDF-15." (PMID 34638326, 2021). "Another important subject relative to the biological activity of GDF15 is tumor genesis." (PMID 34445593, 2021). "Considerable evidence also suggests that GDF15 might contribute to tumor progression through autocrine and paracrine signaling." (PMID 34681812, 2021). "The mutation spectra/counts of miR-216a and GDF15 did not synchronize with the corresponding tumor mutational burden (TMB)." (PMID 34948431, 2021). "We demonstrated that GDF15 downregulation inhibited tumor metastasis." (PMID 33123476, 2020). "In vivo studies using transfected tumor cell lines which are xenografted into immunodeficient mice have suggested, overall, that GDF15 may facilitate tumor growth and spread." (PMID 32502202, 2020). "It is unclear whether these diverse outcomes ensue from cell-intrinsic signaling, which is instigated by GDF-15's action on tumor cells." (PMID 32508832, 2020). "Based on its ability to shield tissues against inflammation, GDF-15 may thus be expected to change the immune contexture within a tumor." (PMID 32508832, 2020). "Conversely, secreted GDF-15 could act as a tumor promoter by facilitating angiogenesis in the tumor microenvironment." (PMID 33193874, 2020). "The neutralization of the anti-inflammatory functions of GDF-15 could potentially enhance tumor-promoting inflammation." (PMID 32508832, 2020). "As previously reported, secreted GDF-15 could regulate the tumor microenvironment and facilitate the proliferation, invasion, and metastasis of tumors by affecting the activity of downstream signaling pathways 10, 13-15." (PMID 33193874, 2020). "GDF-15 is, however, more than a surrogate marker for tumor progression and tumor load." (PMID 32508832, 2020). "Since neutralizing GDF-15 could “heat up” the tumor microenvironment, it may already achieve a benefit in monotherapy." (PMID 32508832, 2020). "It has been previously shown that secretome of tumor cells induced by therapy treatment can promote resistance and tumor progression, and GDF15 could be one of the secreted proteins in the context of cisplatin resistance." (PMID 33086658, 2020). "To determine whether GDF15 affects tumor stroma composition, we used microscopic images of Ki67 stains for cellular segmentation analysis of tumor and non-tumor cells within the tumors from both GDF15-KD and control mice." (PMID 33086658, 2020). "Indeed, by inhibiting dendritic cell maturation and by preventing immune cell recruitment, GDF-15 interferes with priming of T cells by dendritic cells and with infiltration of activated T cells into the tumor microenvironment." (PMID 32508832, 2020). "This suggests that GDF15 could be an important factor in tumor progression by enhancing interferon signaling and DNA repair of tumor cells." (PMID 33086658, 2020). "Alternatively, the highly context-dependent findings might best be explained by GDF-15's action on the tissue context of the tumor cells, i.e., the tumor microenvironment." (PMID 32508832, 2020). "As shown by the canonical pathway comparative analysis of GDF15-NT and GDF15-KD mouse tumor and stroma, pathways that could be responsible for the crosstalk were identified." (PMID 33086658, 2020). "Evidence suggests that GDF15 plays different roles in different stages of tumor progression." (PMID 33062674, 2020). "Thus, using multiple approaches our data indicates that the GDF15 protection from early TRAMP tumor growth requires adaptive immunity including CD8 T cells." (PMID 32502202, 2020).
tumor (continued). "Regardless, it is clear that manipulating GDF15-GFRAL-RET signaling at the same time as tumor implantation (via tumor GDF15 knockdown or overexpression) is different to whole body knockout or overexpression of GDF15 from a transgene throughout the animal lifespan." (PMID 32310257, 2020). "GDF-15 is a member of the TGFβ family with both pro- and anti-tumor activities." (PMID 32519025, 2020). "Considering the attention that GDF-15 has received as a potential prognostic biomarker in neoplastic disease, we examined the serum concentrations of GDF-15 in an ambulatory population within the continuum of MM, ranging from asymptomatic up to overt MM (staged according to ISS)." (PMID 33144847, 2020). "However, depending on tumor type, GDF15 has been shown to be either protumorigenic or antitumorigenic." (PMID 33086658, 2020). "Because tumor growth is a balance between proliferation and apoptosis, we sought to determine whether cell proliferation differed in GDF15-KD mice compared to the control following cisplatin exposure." (PMID 33086658, 2020). "Furthermore, EMT was dramatically repressed in the shGDF15-expressing tumors, in which expression levels of N-Cadherin and Vimentin were obviously reduced, implicating the repression of tumor metastasis after GDF15 abrogation." (PMID 32076610, 2020). "As the propeptide contains a heparan sulphate binding motif, this form of GDF15 can bind to extracellular matrix and thus remain localized to the tumor, from where it might be slowly released to provide a local pool of GDF15." (PMID 32502202, 2020). "In addition, to study the effects of GDF-15 on the chemosensitivity of tumor cells, gemcitabine treatment was administered after downregulating GDF-15 expression by a lentiviral infection system in AsPC-1 cells." (PMID 33201838, 2020). "On the contrary, there are several canonical pathways being activated in the stromal cell component of GDF15-KD tumor after cisplatin treatment compared to the GDF15-NT control such as the RhoGDI signaling pathway and the acute phase response signaling pathway." (PMID 33086658, 2020). "Despite evidence of the tumor-promoting effects of GDF-15, the pathways through which GDF-15 mediates these effects remain unclear." (PMID 33201838, 2020). "In addition, we showed that GDF15 expression can impact the response of both the tumor and stromal cells to cisplatin." (PMID 33086658, 2020). "The crosstalk between secreted GDF15 and the stromal environment may play an important role in developing drug resistance by remodeling the tumor microenvironment as have been observed in other environment-mediated drug resistance." (PMID 33086658, 2020). "Likewise in patients, where larger-sized prostate tumors can be resected, while metastasis is a deadly threat, the pro-metastatic effects of GDF-15 overexpression are likely more relevant than its tumor-suppressive properties." (PMID 32508832, 2020). "However, we did not observe any significant increase in the percentage of Ki67-positive tumor cells in mice after GDF15 KD or a decrease in the percentage of Ki67 after treatment with cisplatin." (PMID 33086658, 2020). "GDF-15 seems to be an integral component of the tumor ME, for which it may serve as a surrogate measure, alongside other indices characterizing disease burden." (PMID 33144847, 2020). "Whilst some other immune cells such as dendritic cells may express CD8-α, in the context of the other available data, this suggests that CD8 T cells mediate the GDF15 induced reduction in TRAMP tumor growth and development." (PMID 32502202, 2020). "Elevated levels of GDF‐15 have indeed been observed in distinct tumour entities." (PMID 31463975, 2019). "Patients with high plasma level of GDF-15 had significantly larger tumor volume (p = 0.008)." (PMID 30645608, 2019).
tumor (continued). "Thus, our findings indicate that the loss of GDF15 expression and reduced RhoA activity resulting from loss of TK1 via shRNA silencing leads to reduced tumor and metastatic activity in LUAD cells." (PMID 31589613, 2019). "However, under pathological conditions, GDF15 expression can be induced in response to diverse cellular stress signals, such as hypoxia/anoxia, inflammation, acute tissue injuries, and tumor processes." (PMID 31772623, 2019). "In particular, we discuss the effect of neurotensin, GDF-15, S1P (including the drug FTY720), and infection with CMV on tumor-associated macrophages (TAM), microglial cells, neutrophil and regulatory T cells (Treg), on the tumor microenvironment." (PMID 29467963, 2018). "Furthermore, IHC revealed that the xenograft tumor tissues formed by HeLa-GDF15 and SiHa-GDF15 cells demonstrated much stronger Ki67 staining score than those formed by control cells (HeLa-GFP and SiHa-GFP) (P < 0.05)." (PMID 29636108, 2018). "We also discovered that KLF5, GCN5, GDF15, and C5aR expression was closely correlated with the tumor size, lymph node metastasis, and TNM stage of NSCLC, indicating that these proteins may have an important function in NSCLC tumorigenesis." (PMID 29773900, 2018). "Besides, GCN5, KLF5, or GDF15 silence reduced cell proliferation in vitro and xenograft tumor growth in vivo." (PMID 29773900, 2018). "Several studies have shown that GDF15 plays an important role in suppressing the tumor progression." (PMID 30542297, 2018). "Tumor suppressor activity of GDF15 was also tested in a transgenic mouse model." (PMID 30542297, 2018). "In conclusion, the chemotherapeutic damage in TACE to HCC could promote tumor angiogenesis via the increased release of GDF15." (PMID 29383859, 2018). "Serum GDF15 level also correlated with the Tumor-Node-Metastasis stage." (PMID 30542297, 2018). "By reducing the concentration of secretory factors such as NT, S1P, GDF-15, from very high to physiological or even lower levels, it may have a destructive effect on the viability of the tumor cell." (PMID 29467963, 2018). "Mice with tumor implants that increased GDF15 into the range found normally circulating in humans were able to gain weight, however; those with increasingly higher levels of circulating GDF15 were found to lose weight progressively." (PMID 30542297, 2018). "In addition to silencing the antitumor immune response, GDF-15 affects cell migration to the tumor niche." (PMID 29467963, 2018). "Additionally, we evaluated GDF15 as a serum tumor biomarker regarding the detection of EOC, especially, as a prognostic marker for prediction of chemotherapy resistance." (PMID 29580231, 2018). "In conclusion, we demonstrate that chemotherapeutic damage of TACE to HCC could promote tumor angiogenesis via the increased release of GDF15." (PMID 29383859, 2018). "The effect of GDF15 on xenograft tumor growth was investigated in vivo." (PMID 28199981, 2017). "Further, MEK inhibition blocked the ability of GDF15 to induce tumor sphere formation, indicating that MEK activation downstream of IGF-1R activation may contribute to GDF15-stimulated EMT." (PMID 29212236, 2017). "Moreover, we further investigated the effects of GDF15 on tumor metastasis in vivo using a mouse model of lung metastasis." (PMID 28199981, 2017). "Elevated expression of GDF15 was previously reported in serum and tumor samples of HCC patients." (PMID 28199981, 2017). "Our data showed that high level of GDF15 in either tumor tissue or serum from CRC patients was positively correlated with metastasis and poor prognosis, which demonstrated that GDF15 might function as a prometastatic factor." (PMID 26497212, 2016).
tumor (continued). "GDF15 serves as a negative prognostic marker in CRC, and high level GDF15 both in tumor tissues and plasma correlate with an increased risk of recurrence and reduced overall survival." (PMID 26497212, 2016). "In addition, a significant correlation between GDF15 expression and the tumor TNM grade was found (P < 0.01)." (PMID 26497212, 2016). "Furthermore, we found that GDF15 level in tumor tissues and serum was significantly increased, in which high GDF15 level correlated with a reduced overall survival in CRC." (PMID 26497212, 2016). "However, upon accumulation of genetic and epigenetic alterations in tumor cells, it switches to promotion of a proinvasive and prometastatic phenotype, accompanied by a progressive increase in the locally secreted GDF15 levels." (PMID 26497212, 2016). "As this class of drug is known to induce expression of MIC-1/GDF15 in both mice and men, this data suggests that tumor suppression may be dependent on the expression of MIC-1/GDF15." (PMID 25695521, 2015). "Metronomic CPA treatment also induced a core set of death-related genes that may be important for innate and/or adaptive immune activation by damaged tumor cells, including Sp110, Mx1, Mx2, Ebi3, Eomes, Tnfsf4, Gdf15, Ddx58, and Dhx58." (PMID 25952672, 2015). "However, trends toward relatively high mean serum GDF15 levels were observed in patients with a larger tumor size or higher viral load, current and former smokers and patients who consumed alcohol or had a family history of HCC." (PMID 25996938, 2015). "Furthermore, knockdown of GDF15 in A2780cis in vivo resulted in enhanced subcutaneous tumor growth in mice but increased sensitivity to carboplatin treatment." (PMID 25490861, 2015). "However, in early stages of the disease, GDF15 can also act as a tumour suppressor and play protective roles, e.g. via inhibiting tumour growth and by pro-apoptotic activities." (PMID 25823874, 2015). "Interestingly, in vivo knockdown of GDF15 in the A2780cis model led to a basal-enhanced tumor growth, but increased sensitivity to carboplatin treatment as compared to the control-transduced A2780cis tumors." (PMID 25490861, 2015). "Moreover, GDF15-overexpressed retarded tumor growth in xenograft animal studies, while GDF15-knockdown enhanced tumor growth." (PMID 26249737, 2015). "In summary, GDF15 knockdown in A2780cis tumors reversed the reduced growth rate and enhanced carboplatin insensitivity back to faster proliferating and carboplatin-sensitive A2780 tumor phenotype." (PMID 25490861, 2015). "However, patients with low/high GDF15 serum concentrations had a clear tendency to show also a low/high GDF15 expression in tumour cells, as indicated by the positive slope of the fitted lines." (PMID 25823874, 2015). "In accordance with microarray and qRT-PCR data, GDF15 levels were increased in plasma (14-fold) during carboplatin short-treatment in A2780 tumor-bearing mice compared to vehicle treatment, but only slightly (twofold) in A2780cis tumor-bearing mice." (PMID 25490861, 2015). "In conclusion, these data show that GDF15 may contribute to carboplatin resistance by suppressing tumor growth through p27." (PMID 25490861, 2015). "GDF15 is overexpressed in many tumor types and following tissue injury, including lung injury." (PMID 24663285, 2014). "Our results showed that at an effector-to-target cell ratio of 80∶1, T cells co-cultured with tumor cell lysate loaded DCs could significantly kill tumor cells, whereas GDF-15 inhibited the CTL activation induced by DCs in a dose-dependent manner." (PMID 24236027, 2013). "In addition, little is known about the interaction between GDF-15 and immune cells in the tumor microenvironment." (PMID 24236027, 2013). "The majority of these studies have suggested that GDF15 is a proapoptotic molecule promoting tumor cell apoptosis, while other studies suggest that GDF15 may facilitate tumor progression." (PMID 23799024, 2013).
tumor (continued). "GDF-15 accelerated the tumor growth rate and increased the tumor size." (PMID 24236027, 2013). "Our studies strongly suggest that MIC-1/GDF15 has complex actions on tumor behavior: it limits local tumor growth but may with advancing disease, promote metastases." (PMID 22952779, 2012). "A previously unrecognized synergy between GDF-15 and inflammatory factors commonly present in tumors was identified and found to promote a disorganized, hyperpermeable vasculature, thereby facilitating tumor nutrient access and impeding effective immune cell infiltration." (PMID 41648434, 2026). "A modified analysis of the NUGC-3 tumor samples showed that PC14586 administration in vivo led to changes in the expression of immune and inflammatory signaling–associated genes and gene sets (TNFSF9, CSF2, IL1A, GDF15, and TNFA signaling and inflammatory response)." (PMID 39945593, 2025). "GDF-15 inhibitors could mitigate this by reducing the impact of the SNS on tumour immunity." (PMID 41294666, 2025). "However, the complex interplay between GDF15 and tumor growth remains unclear, with contradictory findings reported in overexpression and knockdown studies." (PMID 40837873, 2025). "Furthermore, given its involvement in tumor progression and systemic effects, such as cachexia and metabolic dysregulation, targeting GDF15 or its downstream pathways may offer a novel therapeutic strategy." (PMID 40725563, 2025). "For example, a retrospective study including metastatic NSCLC patients treated with the anti-PD-1 antibody nivolumab found that low tumor GDF15 expression was associated with OS, PFS, and ORR, suggesting that GDF15 may identify subsets of patients less likely to benefit from immunotherapy." (PMID 40868185, 2025). "However, it has been suggested that GDF15 upregulation may exert a tumor-suppressive role during the early phases of tumorigenesis, while later acquiring the capacity to promote tumor progression." (PMID 40868185, 2025). "Thus, cleavage at the RXXR site is crucial in determining whether NAG-1/GDF15 exhibits anti- or pro-tumor activity." (PMID 40316530, 2025). "This apparent contradiction may reflect the pleiotropic nature of GDF15, which not only marks local tumor behavior but may also indicate systemic effects, such as inflammation, cachexia, or immune modulation, that contribute to poorer outcomes independently of tumor stage." (PMID 40725563, 2025). "This suggests that elevated GDF15 levels may identify patients at an increased risk of recurrence, regardless of the tumor stage." (PMID 40725563, 2025). "Therefore, GDF15 promotes the occurrence of immune escape and tumor proliferation." (PMID 38365757, 2024). "Therefore, knocking out GDF15 through gene editing could potentially reverse the suppressive tumor immune microenvironment permanently." (PMID 38704691, 2024). "Additionally, osteoblasts secrete GDF-15 to further facilitate tumor development." (PMID 38243240, 2024). "It is reported that high levels of GDF15 could promote tumor cell proliferation and metastasis." (PMID 39697630, 2024). "Interestingly, treating mice with monoclonal antibodies targeting GDF15 could reverse the tumor-induced metabolic changes and promote weight gain in these animals, even with caloric restrictions." (PMID 39697630, 2024). "However, weighing of explanted tumors suggested a reduced tumor mass after anti-GDF-15 treatment." (PMID 37474523, 2023). "Accordingly, GDF-15 may impair long-term tumor control in patients treated with anti-CTLA-4." (PMID 37474523, 2023). "Besides, our results showed that GDF15 was related to angiogenesis, implying that it may affect tumor progression." (PMID 34697897, 2022). "Hence, our findings show a pro-tumor effect of GDF15 resulting from its promotion of GSC stemness." (PMID 33431816, 2021).